CRP (C-reactive protein)
Diseases named in the same sentence as CRP in open-access papers (continued):
Sharing a sentence is not in itself a finding about the gene and the disease.
Obesity (continued). "The mechanisms whereby obesity leads to increased CRP levels are not clearly understood, but inflammatory cytokines such as IL-6 are produced by adipose tissue, and this process is exacerbated in conditions of increased central adiposity." (PMID 35035976, 2022). "Children with overweight and obesity had higher levels of inflammation markers (such as CRP and lymphocytes), worse lipid profiles (lower HDL-C, higher triglycerides, and LDL-C levels), and lower levels of serum iron compared to children with normal weight." (PMID 36498548, 2022). "Overweight and obesity can lead to “low-grade chronic inflammation”, which increases the concentrations of C-reactive protein (CRP) and interleukin (IL)-6 in plasma." (PMID 36353279, 2022). "Based on the BWRP-induced decrease in CRP levels, chronic systemic inflammation seems to play a role in mediating obesity-related epigenetic remodeling and biological aging." (PMID 36012914, 2022). "Previous studies show positive correlations between Leptin, Visfatin, Resistin and Adipsin and circulating inflammatory markers such as IL-6 and CRP in individuals suffering from obesity." (PMID 35684160, 2022). "Proinflammatory state existing in subjects with obesity and blood concentrations of the inflammatory markers, including C-reactive protein, interleukin-6, adipokines, fibrinogen, and PAI-1, are shown to be reduced following bariatric surgery." (PMID 35855391, 2022). "Furthermore, obesity is associated with a low-grade inflammation status, and adipose tissue can secrete several proinflammatory factors, such as C-reactive protein, tumor necrosis factor-α, and interleukin-6, which may exert crucial functions in the pathogenesis of OPLL or OLF." (PMID 35937605, 2022). "In obesity, adipocytes are enlarged and the secretion of inflammatory factors such as high-sensitivity C-reactive protein (hs-CRP) is increased." (PMID 36079719, 2022). "A meta-analysis of CRP demonstrated interactions between obesity and elevated CRP levels that were more marked among women than men, and also among populations from Europe and the United States." (PMID 35035976, 2022). "As such, the proportion of the total effect which was mediated by the effect of obesity on CRP at 45y, was 23.27% (95% CI: 8.64%, 37.90%)." (PMID 35301057, 2022). "Elevated level of CRP among ALL survivors was associated with an increased risk of cardiometabolic complications, including obesity, dyslipidemia, and insulin resistance." (PMID 36142534, 2022). "We observed that 23% of the relationship between obesity in early-adulthood and PF in mid-life was mediated by CRP." (PMID 35301057, 2022). "C-reactive protein (CRP) is a general marker of inflammation that is chronically elevated in obesity, reflecting the low-grade inflammatory state of adipose tissue." (PMID 35922472, 2022). "The proportion of Th1 cells in in visceral rather than subcutaneous adipose is also reported to be significantly correlated with plasma CRP, suggesting the involvement of Th1 cells in obesity-driven inflammation." (PMID 36457551, 2022). "Differences in the serum levels of CRP were found between patients with overweight and obesity (p = 0.0046)." (PMID 36558394, 2022). "In this way, CRP contributes to the pathogenesis of obesity-related diseases, including T2DM and CVD." (PMID 35620114, 2022). "C-reactive protein (CRP), as an indicator of low-grade inflammation, has been considered a possible risk factor for cardiovascular diseases associated with obesity, and CRP also plays as a major determinant of central obesity." (PMID 35379317, 2022). "An obesity-CRP-poor PF pathway is supported by the known functions and downstream effects of adipose tissue and CRP." (PMID 35301057, 2022). "CRP is effectively elicited by IL‐6, which is often increased in obesity, thus explaining the lower ratio found in patients with obesity." (PMID 35837843, 2022).
Obesity (continued). "The results of this meta-analysis showed that aerobic training (AT) and aerobic plus resistance training (AT + RT) reduced the levels of IL-6 and CRP in adolescents with obesity." (PMID 36293806, 2022). "It was shown that the concentration of CRP in the blood is higher in people (prepubertal and adults subjects) with overweight and obesity in relation to people with normal weight, possibly as a result of the production of IL-6 and TNF-alpha by adipose tissue." (PMID 35053667, 2022). "A multi-disciplinary programme aimed at reducing weight through lifestyle changes in pre-menopausal women with obesity reported a reduction of markers of inflammation including CRP." (PMID 34700074, 2022). "CRP can be elevated secondary to obesity, as visceral adipose tissue produces vast amounts of interleukin-6, which stimulate secretion of CRP by the liver." (PMID 34478414, 2022). "Obesity is a chronic pro-inflammatory state, with increased circulating levels of the inflammatory markers C-reactive protein (CRP), interleukin-6 (IL-6) and tumour necrosis factor-alpha (TNF-α)." (PMID 34857870, 2022). "In type 2 diabetes and HTN, obesity and overweight, insulin resistance, and overexpression of pro-inflammatory proteins including C-reactive protein (CRP) and cytokines (IL-1β, IL-6, and TNF-α) contribute to chronic inflammation." (PMID 35361279, 2022). "The combined effect size SMD = −0.40, 95% CI = −0.68~−0.12 (p = 0.005), indicating that training significantly reduced the level of CRP in adolescents with obesity." (PMID 36293806, 2022). "Consistent with these previous findings, we found that CRP levels were significantly higher in our children with obesity." (PMID 36079892, 2022). "Obesity triggers inflammation marked by the secretion of low-grade inflammatory cytokines including interleukin-6, C-reactive protein, and tumor necrosis factor-α, leading to a condition known as “meta-inflammation”." (PMID 35740977, 2022). "We decomposed the total effect of early-adult obesity on mid-life PF into direct and indirect (via CRP) effects, by employing a mediation analysis based on parametric g-computation." (PMID 35301057, 2022). "Favorable C-reactive protein (CRP), serine, glycine, and 3-hydroxybutyrate plasma profiles in RYGB rats were suggestive of reverted obesity risk." (PMID 35163046, 2022). "Model 2 which included the variables “transferrin-saturated and CRP” instead of “iron and HDL-C”, respectively, showed similar results, with a significant positive association between the CRP and overweight/obesity (OR 1.39, 95% CI 1.10–1.76, p = 0.007)." (PMID 36498548, 2022). "exanimated the role of obesity-related factors including CRP, hemoglobin-A1c (HbA1c), sex hormone-binding globulin (SHBG), and testosterone in the association of adiposity and CRC risk." (PMID 36407320, 2022). "In the reverse MR analysis, we also observed effects of BMI (both childhood and adult) on obesity-related biomarkers, such as CRP, IGF1, insulin, leptin, and TNFR2." (PMID 36253437, 2022). "C-reactive protein (CRP), interleukin 6 (IL-6) and fibrinogen are associated with obesity and affect vascular structure and endothelial function." (PMID 35013379, 2022). "Low-grade inflammation due to obesity drives human C-reactive protein (CRP) production by hepatocytes in vitro and in vivo in humans." (PMID 35563589, 2022). "The association between TNF-alpha and other surrogate markers of inflammation such as c-reactive protein is also strengthened obesity in GDM." (PMID 36992779, 2022). "Anthropometric indices of obesity, fasting plasma glucose, blood pressure, blood lipids, and C-reactive protein were evaluated." (PMID 35784542, 2022). "Menopause, obesity, decreased physical activity, unhealthy habits, and diets are the most important factors in increasing serum CRP, insofar as some researchers have even considered it to be the most important predictor of inflammatory diseases." (PMID 35719707, 2022).
Obesity (continued). "Biochemical analysis of serum 6 months after BS showed improvement in most obesity-related parameters (CRP, GGT, LDL, triglyceride, glucose, HBA1c)." (PMID 36431314, 2022). "Individuals with obesity also had CRP levels at 45y which were approximately 80% higher than individuals who were not obese." (PMID 35301057, 2022). "Although further studies are required to investigate the relation between high BMI and CRP in IBD, CRP is a marker for inflammation and has been implicated in IBD and obesity." (PMID 35276983, 2022). "The concentration of 25(OH)D3 and CRP among children and adolescents with obesity were 2.9 ng/mL and 2.4 mg/dL, respectively, higher than those without obesity." (PMID 35379317, 2022). "Metabolically unhealthy obesity leads to the overexpression of CRP and IL-6, resulting in low-grade chronic inflammation." (PMID 34991564, 2022). "Increased levels of maternal CRP and TNF-α, pro-inflammatory cytokines that are elevated in mothers with obesity, have been associated with wheezing and lower respiratory tract infections in offspring." (PMID 36189369, 2022). "In the inflammatory processes of obesity and PD, the concentration of inflammatory markers increases; one of these markers is C-reactive protein (CRP)." (PMID 36547041, 2022). "High-sensitivity CRP (hs-CRP) is considered an obesity-independent surrogate marker of severity of NAFLD, especially the development of NASH." (PMID 36139429, 2022). "Obesity in early-adulthood was associated with over twice the odds of poor PF in mid-life, with approximately 23% of the obesity effect operating via a downstream effect on CRP." (PMID 35301057, 2022). "Overall, 9 weeks of probiotic and magnesium supplementation resulted in decreased CRP levels in individuals with obesity and depressed mood." (PMID 36245482, 2022). "Interpretations on biological sex and association with CRP rely heavily on obesity indices including BMI, PBF, and WHR, which were also associated with CRP concentrations in this study and tend to vary in women and men." (PMID 35821205, 2022). "Other markers of inflammation such as C-reactive protein are also increased in patients with obesity (especially in those with abdominal obesity)." (PMID 35955431, 2022). "Circulating IL-6 levels are shown to positively correlate with CRP levels and CRP was shown to be elevated in obesity and IBD." (PMID 35276983, 2022). "The state of inflammation in obesity is associated with adipose tissue dysfunction, which increases the secretion of pro-inflammatory cytokines such as TNF-α, CRP, and IL-6." (PMID 35740977, 2022). "The low-grade inflammation of adipose tissue found in obesity is characterized by the abnormal production of cytokines, an elevated synthesis of acute-phase proteins such as CRP, and the activation of pro-inflammatory signaling pathways." (PMID 36401194, 2022). "Obesity and OSA are conditions linked to higher levels of inflammatory cytokines in nasal tissue, such as C-reactive protein, tumor necrosis factor alpha, interleukins, and granulocyte-macrophage colony-stimulating factor." (PMID 32782124, 2022). "This study investigated the effects of folic acid on obesity and high-sensitivity C-reactive protein (CRP) levels." (PMID 36079719, 2022). "In both BMI- and WC-defined obesity, our study found that the MuHO phenotype has the highest mean or median hs-CRP, ALT, and HOMA-IR values compared to other phenotypes." (PMID 35267891, 2022). "According to some studies, the severity of the symptoms hypertension, dyslipidemia, and obesity are significantly correlated with insulin resistance and elevated CRP concentrations." (PMID 36160290, 2022). "The levels of oxidation indices, such as high-sensitivity C-reactive protein (hs-CRP) and uric acid (UA), were higher in the obesity group, indicating the low-grade inflammation in children with obesity." (PMID 36061547, 2022).
Obesity (continued). "IL-6 induces the hepatic synthesis of C-reactive protein (CRP) and its levels have been linked with visceral adiposity but its role in obesity and insulin resistance is controversial." (PMID 35886175, 2022). "The aim of this study was to determine the metabolic-obesity phenotypes of women of reproductive age using the CMDS and EOSS and explore associations with inflammation (C3 and CRP)." (PMID 35306495, 2022). "The highest predicted probabilities of intermediate hyperglycemia and obesity occurred around the upper limits of CRP and insulin and the lower limits of adiponectin." (PMID 35757631, 2022). "The secretion of adipokines (leptin and adiponectin) and cytokines (C-reactive protein, TNF, IL-6, IL-8) driven by adipose tissue in obesity can alter the expression and secretion of factors associated with angiogenesis in the primary tumor." (PMID 36014894, 2022). "The data obtained in the different studies show a significant increase in IL-6 and CRP values in the PD and obesity groups compared to the control groups, finding a positive correlation with PD and obesity." (PMID 36547041, 2022). "In patients with successful expectant management, obesity (body mass index ≥ 30) and high WBC and CRP level at admission were significantly associated with prolonged hospitalization." (PMID 35978309, 2022). "Last, BMI demonstrated a quite robust protective effect on OCD conditioned on CRP and IL-6 signaling, in accordance with observational data that OCD is associated with reduced odds of obesity." (PMID 35385317, 2022). "Body mass index (BMI), body fat content, and metabolic laboratory parameters such as blood lipids, glucose homeostasis and c-reactive protein were significantly higher in the obesity group." (PMID 35432192, 2022). "Finally, we tested the hypothesis that lifestyle changes in the UK predisposing individuals to obesity would influence levels of CRP, predicting that increased markers of overweight/obesity would elevate levels of CRP in adulthood, and again that women would be more vulnerable to these effects." (PMID 35035976, 2022). "It remains to be seen how rising levels of overweight and obesity within LMICs like Bangladesh will also affect levels of CRP across the life course, particularly among those who continue living in areas with high pathogen exposures." (PMID 35035976, 2022). "One possibility is the consistent reduction in the obesity proinflammatory state indicated by lower levels of C reactive protein and interleukin-6 (IL-6) after bariatric surgery." (PMID 36033567, 2022). "More attention in the intervention of overweight and obesity should be paid to boys living in urban areas, and high serum concentration of CRP should also be concerned." (PMID 35379317, 2022). "It is notable that CRP ≥2 mg/L was highly prevalent in all of the chronic diseases studied, ranging from 39.6% of people with cancer to 85.6% of people with class 3 obesity, and was more prevalent in people with greater multimorbidity." (PMID 35535512, 2022). "The aim of this study was to examine the possible association between serum micronutrients (vitamin D, retinol, zinc), C-reactive protein (CRP), and obesity among children and adolescents." (PMID 35379317, 2022). "Patients with obesity produce higher levels of cytokines such as IL-6, C-reactive protein and TNF-α than normoweight individuals." (PMID 35955431, 2022). "Several studies have also reported direct associations between prepregnancy obesity and elevated gestational CRP levels, and have suggested that inflammation is likely to be a mediator between prepregnancy obesity and adverse pregnancy outcomes." (PMID 35768766, 2022). "A negative correlation between the quantity of B. fragilis and the anthropometric parameters of obesity (r = −0.48) and C reactive protein level (r = −0.36) in serum was established." (PMID 36013992, 2022).
Obesity (continued). "We included a large sample size and provided comprehensive analysis on the interaction between DP and NPs with the grade of CRP in the general adult population, stratified by gender, obesity and metabolic health." (PMID 36082032, 2022). "Both T2DM and obesity exacerbate the inflammatory response, leading to increased serum concentrations of inflammatory biomarkers such as C-reactive protein." (PMID 36465631, 2022). "In the present study, hs-CRP levels were significantly high at the baseline, and this finding supported the association between GDM, obesity, and inflammation." (PMID 36145254, 2022). "These include dyslipidemia, hypertension, obesity, smoking and sedentary lifestyle, as well as advanced glycation end products (AGEs) and its receptors and C-reactive protein (CRP)." (PMID 35626326, 2022). "Serum ferritin, uric acid, triglycerides, LDL-C, globulin, and CRP levels were significantly higher among the overweight/obesity group than in the normal weight group." (PMID 36498548, 2022). "Advances in canine obesity is still in its early stage; however, a decrease of inflammatory markers, such as CRP and Hp, has been observed after weight loss in previous studies, suggesting that also dogs may suffer from a compelling association between low-grade inflammatory state and obesity." (PMID 36713218, 2022). "CRP is well known marker for obesity-related inflammation and the Mets, thus we measured its levels." (PMID 35318405, 2022). "In humans, neutrophil counts are higher in hyperlipidaemia, hyperglycaemia, and insulin resistance even in healthy individuals, and are accompanied with higher lymphocyte and monocyte counts and higher CRP levels in obesity and the metabolic syndrome." (PMID 35614088, 2022). "C-reactive protein is an acute phase protein expressed in response to systemic inflammation, since obesity can trigger an increased local inflammatory response to an external stimulus, such as dental plaque." (PMID 36547041, 2022). "Low-income status and smoking activity contributed most to elevated CRP levels among older Black males, whereas obesity mainly contributed to elevated CRP levels in older Black females." (PMID 35432388, 2022). "Regarding the effect of different training modalities on CRP levels in adolescents with obesity, there was heterogeneity between the studies (I2 = 76%, p < 0.00001)." (PMID 36293806, 2022). "After the univariate analysis for thrombotic events, significant variables (age, arterial hypertension, obesity, previous thrombosis, elevated CRP, troponin and elevated D-dimer) were included in a binary logistic regression analysis with the presence of aPL." (PMID 35812410, 2022). "Several pronociceptive and antinociceptive pathways have suggested to have an important role in the relation between obesity and pain sensitivity, particularly the presence of inflammatory markers such as interleukin-6 (IL-6) and C-reactive protein (CRP)." (PMID 35743474, 2022). "The decrease in anthropometric parameters of obesity, liver enzyme level correction, reduction in C reactive protein and triglyceride concentrations were revealed after IC usage." (PMID 36013992, 2022). "Circulating concentrations of the inflammatory markers fibrinogen (P<0.001), homocysteine (P=0.037), CRP (P=0.033) and vWF (P=0.029) were increased in patients with obesity." (PMID 35222417, 2022). "Future studies need to be targeted at patients with evidence of inflammation; however, it should be noted that peripheral inflammatory markers such as CRP can fluctuate, and are affected by confounding factors such as obesity and smoking." (PMID 36217374, 2022). "Among them, AT + RT was more effective than other training modalities in reducing IL-6 and CRP in adolescents with obesity." (PMID 36293806, 2022). "Elderly persons more frequently suffer from bacterial and viral infection/inflammation as well as obesity and cardiovascular diseases in peripheral systems, which lead to elevated CRP levels." (PMID 36550123, 2022).